DGKA (diacylglycerol kinase alpha)
Diseases named in the same sentence as DGKA in open-access papers (continued):
Sharing a sentence is not in itself a finding about the gene and the disease.
tumor (continued). "In summary, DGKα upregulation in 3D context links the function of this enzyme to tumor survival and drug resistance mechanisms, and further supports development of new drug therapies based on this lipid kinase." (PMID 25339152, 2014). "DGKα expression is increased in tumors compared to adjacent non-cancerous tissue, as well as in metastasis of the original tumor." (PMID 25339152, 2014). "Investigation of tumor-infiltrating CD8 cells in human renal cell carcinoma patients showed increased DGKα activity and diminished signaling via MAPK pathways, as compared to CD8 cells that were present in non-tumor areas of the kidney." (PMID 23847619, 2013). "At the same time, DGKα and DGKζ control T cell function during activation and anergy, responses to pathogen and tumor, and the development of iNKT and T cells." (PMID 23531532, 2013). "Indeed, DGKα is a major determinant of T cell anergy and together with enhanced DGKζ, makes tumor‐infiltrating CD8 and NK lymphocytes hyporesponsive by downmodulating DAG signaling to MAPK pathway." (PMID 40859612, 2026). "Twelve (29%) of the 42 tumor specimens were positive for DGKα." (PMID 40013327, 2025). "DGKα, along with DGKζ, is recognized for its role in promoting T-cell anergy, a process that limits T-cell activation in the tumor microenvironment and supports tumor survival via PA generation." (PMID 39684917, 2024). "Increased DGKα expression may increase the dependence of cancer growth on DGKα function, and pathological evaluation of tumor tissue can indicate the targets of DGKα inhibitory therapy." (PMID 38716625, 2024). "In the multivariate analysis, tumor number and DGKα positivity were independent prognostic factors." (PMID 38716625, 2024). "Recent reports suggest that inhibiting DGKα could help reverse T lymphocyte exhaustion, thereby promoting more effective anti-tumor T cell responses." (PMID 39684917, 2024). "In addition, DGKα and DGKζ contribute to tumour cell immune escape, and their inhibition rescues defective anti-tumour killing activity in tumour-specific exhausted T cells." (PMID 37138877, 2023). "Considering that AML is a complex and incurable disease with adverse clinical outcomes, it may be a feasible choice to reuse ritanserin as a DGKα inhibitor for tumor indications." (PMID 37392305, 2023). "Intriguingly, SAP is a novel PD-1 signal transducer suggesting that this pathway may also be involved in the control of DGKα activity of tumour infiltrating lymphocytes." (PMID 37138877, 2023). "As Drosophila Ras-driven, polarity-impaired tumours have unrestrained activity of aPKC [an important factor in inducing tumour growth], which occurs via Hippo pathway inhibition, it is possible that by inhibiting DGKα, the elevated aPKC activity and Hippo pathway impairment would be rescued." (PMID 36861754, 2023). "DGKα/ζ inhibition enhances activation and effector function of tumor-specific CD8 T cells." (PMID 38000024, 2023). "The investigation of the involvement of DAG-regulated signalling pathways in SCRIBRNAi/H-RASG12V tumour growth and the effect of inhibition of DGKα on these pathways will be important in providing a full picture of the involvement of DGKα in Ras-driven cancers." (PMID 36861754, 2023). "DGKα has also been shown to promote tumor invasion and progression by generating PA at invasive pseudopods triggering the localization of atypical PKC, which control Rac-mediated protrusion elongation and Rab-coupling protein (RCP)-dependent integrin recycling." (PMID 36358678, 2022). "In fact, specific knockout of DGKζ may have stronger T cell-promoting effects than specific DGKα knockout, and this translated to greater anti-tumor activity in one report testing three syngeneic tumor models in mice." (PMID 35267577, 2022). "Hence, the role of DGKα in bridging membrane morphology with the regulation of specific molecular species of DAG/PA in invasive protrusion during tumor migration requires further studies." (PMID 36358678, 2022).
tumor (continued). "The overexpression of DGKα supports tumor cell proliferation." (PMID 36613836, 2022). "Given that tumor-associated macrophages (TAMs) have powerful tumor-promoting effects, it must be assessed whether DGKα inhibition promotes or suppresses this pro-tumor macrophage activity; these studies are ongoing." (PMID 34804012, 2021). "Therefore, if a DGKα-specific inhibitor is developed, it would reversely and simultaneously inhibit tumor cell proliferation and enhance T cell function and consequently can be a dual effective drug." (PMID 34680338, 2021). "Particularly, DGKα reduces the antitumor immune reaction of tumor-infiltrating CD8+ T cells." (PMID 34680338, 2021). "DGKα induces tumor growth in vivo through the formation of a DGKα/Src complex, which activates Src." (PMID 32456226, 2020). "In addition, they revealed DGKA as a negative regulator of TNF-α-induced apoptosis in these tumor cells." (PMID 32477950, 2020). "Comprehensive expression patterns in tumor cells reveal that the interplay with tumor-type specific activated signaling pathways might control DGKA function." (PMID 32477950, 2020). "DGKA inhibitors, therefore, offer not only a promising way to manipulate DGKA activity for therapeutic purposes in tumor cells but they might also be helpful to confine a perpetuated wound healing response leading to fibrosis." (PMID 32477950, 2020). "For instance, in T cells, the inhibition of DGKα activity may generate a simultaneous response of reinforcing T cell attack on tumor cells, while directly inhibiting tumor growth." (PMID 32722576, 2020). "Furthermore, the ability of exosome-treated fibroblasts to assemble ECM which supported enhanced tumour cell migration was completely opposed by inhibition of DGKα (during the ECM deposition period)." (PMID 30498210, 2018). "Although, a preponderance of evidence suggested that the decreased tumor growth in this model resulted from inhibition of DGKα within the tumor cells, modulation of immune activity was not assessed, and could have been contributory." (PMID 27800476, 2016). "Recently, a more specific inhibitor for DGKα has been developed that may be useful to extend these studies into additional tumor models." (PMID 27800476, 2016). "Here we tested the hypothesis that DGKα expression in tumor cells contributes to oncogenic SFK functions." (PMID 25339152, 2014). "By sustaining Src activation, increased DGKα levels might limit the deleterious effect of PI3K/Akt inhibitors on tumor survival." (PMID 25339152, 2014). "The two most highly expressed DGKs in T cells, DGKα and DGKζ, are clearly involved in regulating many processes: T cell selection, iNKT cell development, T cell activation, T cell anergy, T cell responses to pathogen, and T cell anti-tumor responses." (PMID 23531532, 2013). "As deletion of DGKα or DGKζ disrupts anergy formation and promotes T cell activation, deletion of these molecules may also enhance T cell responses to tumor." (PMID 23531532, 2013). "Indeed, tumour infiltrating lymphocytes feature reduced WASp activation while active WASp potentiates T cells and NK lytic function similarly to what was observed with DGKα inhibitors." (PMID 37138877, 2023). "In addition, the DEGs in the DGKα high-risk group were enriched in the Jak-Stat/MAPK signaling pathway, whose activation induces partial AML production and promotes tumor growth, and some AML patients are resistant to conventional treatment due to MAPK pathway activation." (PMID 37392305, 2023). "However, the function of DGKα in cancer is controversial as it might also function as a tumor suppressor." (PMID 32962151, 2020). "This suggests that DGKA inhibition might be an interesting strategy for tumor therapy." (PMID 32477950, 2020).
tumor (continued). "Moreover, DGKα is involved in inflammation in tumor cells by positively regulating tumor necrosis factor α (TNFα)-induced nuclear factor kappa-light-chain-enhancer of activated B cells (NF-κB) activation via a PKCζ-mediated Ser311 phosphorylation of the NF-κB subunit p65/RelA." (PMID 32722576, 2020). "Our results identify DGKα-mediated stabilization of Src activation as an important mechanism in tumor growth, and suggest that targeting this enzyme, alone or in combination with other inhibitors in wide clinical use, could constitute a treatment strategy for aggressive forms of cancer." (PMID 25339152, 2014). "Using healthy donor CD34+ cells as a reference, we detected overexpression of DGKA, DGKG, DGKD and DGKQ in tumor samples, while DGKH and DGKZ were unchanged." (PMID 37509516, 2023). "ESCC TAM-released CCL22 promoted tumor invasion and reduced patient survival via activation of the CCR4/DGKα/FAK complex in ESCC cells, revealing opportunities for targeting the tumor-promoting microenvironment to achieve anticancer effects." (PMID 37198402, 2023). "As ritanserin inhibits both DGKα and serotonin receptors, we wished to determine whether Dgk or serotonin receptors are the key target for ritanserin in Drosophila in reducing scrib−/RasV12 tumour size in cooperation with trametinib by analysing specific DGKα or serotonin receptor inhibitors." (PMID 36861754, 2023). "Using a dual DGKα/ζ inhibitor (DGKi), tumor-specific CD8 T cells with different affinities (TRP1high and TRP1low), and altered peptide ligands, we demonstrate that inhibition of DGKα/ζ can lower the signaling threshold for T cell priming." (PMID 38000024, 2023). "Combined with the observation that DGKα promotes tumor metastasis by directly activating the FAK/AKT pathway, the results of the present study augmented the evidence that the DGKα/FAK axis contributes to ESCC progression in the context of the TME." (PMID 35962191, 2022). "The potential for DGKα inhibition to block or reverse T cell anergy also suggests the potential of DGKα inhibition to boost immunotherapy against GBM, which is generally considered an immunologically “cold” tumor." (PMID 35267577, 2022). "Other references have also suggested the potential for DGKα inhibition to increase T cell activity against tumors, and recently DGKα inhibition has been shown to mitigate T cell exhaustion —which may be a more prominent mechanism than anergy for weakening anti-tumor T cell activity." (PMID 35267577, 2022). "Downregulation of DGKA and its downstream targets HIF-1α and mTOR resulted in suppression of tumor cell migration and survival." (PMID 32477950, 2020). "The inhibition of DGKα inhibited the recruitment of RCP to allow α5β1 integrin recycling and promote the invasiveness of tumor cells, while the inhibition of PLD, which also generates PA, did not affect its recruitment." (PMID 32962151, 2020). "The high level of DGKα and inhibited MAPK pathways can lead to the dysfunction of human tumor-infiltrating CD8+ T cells (pro-tumoral), which is reversible upon treatment with low-dose of IL-2 to suppress DGKα." (PMID 32962151, 2020). "DGKα is up-regulated in hypofunctional OT-I T cells in B16 ovalbumin (OVA)-expressing tumors and therapeutic inhibition of DGKα combined with PD-1 blockade for improved tumor control." (PMID 38000024, 2023). "In addition, it has been shown that in tumor infiltrating CD8 cells, increased DGKα activity led to defects in the exocytosis of granules and lytic function of these cells." (PMID 36358678, 2022). "Remarkably, the cytotoxic activity of DGKA attenuation was observed in tumor cells but not in normal cells." (PMID 32477950, 2020). "Although a direct comparison has not to-date been performed comparing tumor growth in DGKα−/− and DGKζ−/− mice, future studies will undoubtedly provide additional comparisons between the two genotypes with respect to T cell anti-tumor immunity." (PMID 27800476, 2016).
tumor (continued). "Nonetheless, the mechanisms by which DGKα contributes to these processes, and the exact tumor context for which DGKα is an effective target have not been elucidated." (PMID 25339152, 2014). "Even in tumor samples, DGKα‐positive and ‐negative specimens were evidently distinguishable." (PMID 40013327, 2025). "Recent studies reported that DAG kinase α (DGKα) facilitated phosphatidic acid synthesis by consuming DAG to negatively regulate the lipogenic transcription factor SREBP-1 in CRC tumor cells, implying the signal transduction function of DAG in controlling tumor growth." (PMID 39436710, 2024). "Importantly, two compounds were confirmed to display synergism (defined by a greater than additive effect) with trametinib in reducing tumour size: volasertib (Polo-like kinase inhibitor) (Schöffski, 2009) and ritanserin [serotonin receptor 5-HT2A/2C and DGKα inhibitor]." (PMID 36861754, 2023). "We previously reported in vitro synergistic activity combining a DGKα-inhibiting compound with radiation against GBM stem-like cells, and our unpublished data also suggest broad in vitro synergistic activity against GBM with combinations of a DGKα inhibitor and several classes of anti-tumor agents." (PMID 35267577, 2022). "Previous studies have demonstrated that DGKα and ζ play crucial roles in T cell development, activation, anergy, and survival, and CD8 T cell-mediated anti-viral immune responses, iNKT cell development, regulatory T cell differentiation, and anti-tumor immune responses." (PMID 32010133, 2019). "Our findings raise many questions that remain to be investigated, such as whether DGKα activity is elevated in Ras-driven polarity-impaired cells and, if so, how this occurs, and whether increased PA signalling or decreased DAG signalling provide the critical function of DGKα in tumour growth." (PMID 36861754, 2023). "Interestingly, this study showed that ritanserin, a DGKα-targeted inhibitor, may participate in the phospholipase D (PLD) signaling pathway, also negatively regulating the Jak-Stat and MAPK signaling pathways and exerting anti-AML tumor activity." (PMID 37392305, 2023).
cancer (40 papers, 2014 to 2026). A tumor composed of atypical neoplastic, often pleomorphic cells that invade other tissues. "Among the ten DGK-encoding genes, DGKA and DGKZ, which code for DGKα and DGKζ proteins, respectively, are the most extensively investigated owing to their central involvement in regulating immune responses, cancer immunotolerance, and tumorigenesis." (PMID 41227366, 2025). "As expected, DGKα-selective inhibitors and DGKα-specific siRNA caused apoptosis and inhibited the proliferation and epithelial–mesenchymal transition of several cancer cell lines." (PMID 36791913, 2023). "Among the enzyme isoforms, DGKα is the most studied and is reported to be associated with the development and progression of different types of cancer." (PMID 36613836, 2022). "The association between DGKα and cancer as well as its role in immunosuppression (i.e., T cell anergy) has attracted great attention to DGKα as a potential molecular target in immunotherapy." (PMID 36358678, 2022). "While DAG attenuation has been associated with the majority of DGKα roles in T cell biology, it seems that the role of DGKα in cancer cell biology is mainly associated with PA production." (PMID 36358678, 2022). "Apoptosis induction of cancer cells (direct effect) and cancer immunity (indirect effect) induced by DGKα inhibition synergistically cause damage to cancer cells." (PMID 34680338, 2021). "Furthermore, DGKα expression intensity was correlated with the positive rate of Ki‐67 cells and was found to be a factor associated with cancer cell proliferation." (PMID 38716625, 2024). "Pathological DGKα expression in ICC was a cancer proliferation marker associated with recurrence." (PMID 38716625, 2024). "Overactive DGKα and/or DGKζ has been implicated in defective tumor immune responses, and development of selective inhibitors against these T cell-specific DGKs is being pursued as an immunotherapy strategy in cancer." (PMID 37292058, 2023). "Interestingly, DGKA knockdown or inhibition induces a stronger cytotoxicity in cancer cells than in normal cells, underlining again that the amount of DGKA might determine its cellular effects." (PMID 32477950, 2020). "Currently, several clinical trials are investigating the use of DGKα or DGKζ inhibitors either as monotherapy or in combination with other cancer treatments." (PMID 40859612, 2026). "All of this makes DGKα/ζ inhibitors interesting for cancer immunotherapy as they offer a double effect: they potentiate immunesurveillance and decrease cancer cell growth." (PMID 40859612, 2026). "IHC staining revealed that DGKα‐positive cases had significantly worse recurrence‐free and cancer‐specific survival rates (p = 0.036 and = 0.003, respectively)." (PMID 40013327, 2025). "The observed synergistic effect of combining PD-1/PD-L1 blockade with DGKα inhibition presents a promising strategy to enhance the efficacy of cancer immunotherapy." (PMID 39684917, 2024). "DGKα was reported as a regulator of T cells and DGKα inhibitor is expected as a target of cancer immunotherapy." (PMID 38716625, 2024). "First, DGKα expression in cancer cells was qualitatively classified into four groups (−, 1+, 2+, 3+) and divided into two groups (DGKα− and DGKα+1 + to 3+)." (PMID 38716625, 2024). "This dual functionality poses challenges for cancer therapy but also underscores the potential of targeting DGKα to improve treatment outcomes, particularly in CAR-T cell therapies." (PMID 39684917, 2024). "It is widely known that DGKα phosphorylates DAG to produce PA and that PA generated by DGKα is essential for the growth and anti-apoptotic properties of cancer cells." (PMID 37392305, 2023). "Our results reveal that targeting Ras-driven human cancers with Ras pathway and DGKα inhibitors should be an effective combination drug therapy." (PMID 36861754, 2023).